IDH1 (isocitrate dehydrogenase (NADP(+)) 1)
Diseases named in the same sentence as IDH1 in open-access papers (continued):
Sharing a sentence is not in itself a finding about the gene and the disease.
myelodysplastic syndrome (57 papers, 2010 to 2025). A clonal hematopoietic disorder characterized by dysplasia and ineffective hematopoiesis in one or more of the hematopoietic cell lines. "Conversely, in AML and myelodysplastic syndromes, patients with IDH1 mutations have shown poorer overall survival than IDH‐WT patients." (PMID 35526267, 2022). "More recently, IDH1/2 mutations were found in chronic myeloproliferative cancers and myelodysplastic syndromes." (PMID 29439493, 2018). "In contrast, IDH1 mutations predict poor prognosis in myeloproliferative neoplasms and myelodysplastic syndrome." (PMID 27655638, 2016). "Moreover, IDH1/2 mutation status predicted relapse or disease evolution in 100% of cases if we included the patient who developed myelodysplastic syndrome." (PMID 26486081, 2015). "IDH1/IDH2 mutations increase the risk of transformation from myelodysplastic syndrome (MDS) to high-risk AML and are associated with poor prognosis in AML, underscoring their role in disease progression." (PMID 41295305, 2025). "Similarly, the scrutiny of ivosidenib, a pharmaceutical agent developed for the treatment of relapsed or refractory myelodysplastic syndromes (MDS) characterized by IDH1 mutations, provides a compelling motivation for investigating metabolic rewiring mechanisms within diverse cancer types." (PMID 39403716, 2024). "Interestingly, amongst IDH1-mutated myelodysplastic syndrome (MDS) patients who were refractory to therapy with hypomethylating agents, Ivosidenib appeared to have a substantial efficacy, though the subgroup was small (n = 12)." (PMID 32477567, 2020). "Recent genomic sequencing efforts have identified a number of recurrent mutations in myelodysplastic syndromes (MDS) that may contribute to disease progression and overall survival, including mutations in isocitrate dehydrogenases 1 and 2 (IDH1 and IDH2)." (PMID 24936872, 2014). "IDH1 and IDH2 have been reported to be frequently mutated in AML, Myelodysplastic Syndromes (MDS) and chronic Myeloproliferative Neoplasms (MPNs), the most frequent mutations being single-nucleotide variants involving the exon 4 at the arginine hotspot R140 or R172." (PMID 35741115, 2022). "A previous study in patients with myelodysplastic syndromes (MDS) and chronic myelomonocytic leukemia (CMML) showed that smoking more than two packs per day or smoking for more than 40 years were associated with IDH1 mutations." (PMID 32856857, 2020). "Both IDH1 and IDH2 gene mutations are found in approximately 20% of AML as well as 12% of myelodysplastic syndrome (MDS) especially in high-risk cases." (PMID 35216478, 2022). "It has been tested in ongoing phase I/II clinical trials in patients with IDH1-mutated relapsed, refractory AML, and myelodysplastic syndrome (MDS), both in monotherapy and combination with azacitidine." (PMID 33182517, 2020). "Shortly thereafter, recurrent IDH1/2 mutations were noted in AML in 2009, along with several other solid tumors and myelodysplastic syndrome (MDS)." (PMID 29882807, 2018). "In another patient with AML, which likely evolved from a myelodysplastic syndrome (MDS), the MDS and secondary AML samples shared a mutation in IDH1 and the AML gained additional mutations only in NRAS and WT1 genes." (PMID 29312904, 2017). "Genes that regulate DNA methylation and demethylation (e.g., DNMT3A, IDH1 and IDH2, TET2) are commonly mutated in adult AML and myelodysplastic syndromes (MDS), although the frequency of these mutations appears much lower in pediatric AML." (PMID 24672775, 2014).
myelodysplastic syndrome (continued). "Intriguingly, IDH1 and IDH2 mutations were also found in other myeloid disorders such as myeloproliferative neoplasms (MPN) and myelodysplastic syndrome (MDS) which have a propensity to AML development, although at a much lower frequency than AML." (PMID 22397365, 2012). "Finally, gain-of-function mutations in the IDH1 and IDH2 genes have been found in a small number of individuals with myelodysplastic syndromes (MDS) and MPNs." (PMID 40699626, 2025). "One important example is isocitrate dehydrogenase 1 (IDH1) mutation, which has important clinical significance and was found in GBM and myeloid malignancies, such as acute myelocytic leukaemia (AML) and myelodysplastic syndromes (MDS)." (PMID 31578148, 2019). "Differently from myelodysplastic syndrome (MDS), their efficacy in AML is independent of the mutational status of epigenetic modifiers such as IDH1, IDH2, DNMT3A and TET2." (PMID 34439275, 2021). "Meanwhile in 2009, IDH1 mutation was reported in a subset of AML patients lacking specific chromosomal aberrations and in 2010, IDH2 mutation was identified in AML, myelodysplastic syndrome (MDS), and myeloproliferative neoplasms (MPN)." (PMID 22397365, 2012).
intrahepatic cholangiocarcinoma (56 papers, 2014 to 2026). A carcinoma that arises from the intrahepatic bile duct epithelium in any site of the intrahepatic biliary tree. "Mutations in isocitrate dehydrogenase 1 (IDH1) occur in 10% to 25% of intrahepatic cholangiocarcinoma (iCCA) cases." (PMID 41747217, 2026). "An IDH1/2 mutation is found in approximately 28% of intrahepatic cholangiocarcinomas and approximately 7% in extrahepatic cholangiocarcinomas." (PMID 40075667, 2025). "Mutations in IDH1/2 are found in approximately 13%–36% of intrahepatic cholangiocarcinoma cases and are less common in extrahepatic cholangiocarcinoma, constituting less than 1% of instances." (PMID 39156971, 2024). "The presence of IDH1 R132C mutation was highly suggestive of intrahepatic cholangiocarcinoma and led to this patient enrolling in a clinical trial." (PMID 36933203, 2023). "IDH1/2 mutations are detected in 13–36% of intrahepatic cholangiocarcinoma and <1% of extrahepatic cholangiocarcinoma, with more women harboring IDH-1 mutations than men." (PMID 38203714, 2023). "At present, small-molecule inhibitors of IDH1 mutated enzyme are under investigation in preclinical and clinical phases as promising innovative treatments for IDH1-mutated intrahepatic cholangiocarcinomas." (PMID 32824685, 2020). "In addition, ivosidenib, an IDH1 inhibitor, is available for the treatment of IDH1 mutations, which are considered positive in 10–20% of intrahepatic cholangiocarcinoma." (PMID 37046493, 2023). "IDH1 and 2 mutations have been also found in intrahepatic cholangiocarcinoma (ICC, ~20% cases)." (PMID 35055016, 2022). "Although intrahepatic cholangiocarcinoma (iCCA) may harbour IDH1/2 mutations, the contribution of TET2 to carcinogenesis remains unknown." (PMID 34905094, 2022). "For example, we enrolled a patient with an unknown primary cancer with intra-abdominal metastases that was found to harbor a somatic IDH1 p.Arg132Cys variant, leading to the reclassification as a likely intrahepatic cholangiocarcinoma." (PMID 27782854, 2016). "However, patients with intrahepatic cholangiocarcinoma harbor frequent genetic alterations such as isocitrate dehydrogenase (IDH)-1 (20.6–29.1%) and -2 (2.5–4.4%) mutations and fibroblast growth factor receptor 2 (FGFR2) fusions (10–15%), which can be treated with IDH1/2 or FGFR2 inhibitors." (PMID 39660136, 2024). "International guidelines recommend ivosidenib followed by modified FOLFOX (mFOLFOX) for advanced intrahepatic cholangiocarcinoma (ICC) with isocitrate dehydrogenase 1 (IDH1) mutations." (PMID 38778261, 2024). "The last group was enriched for individuals with a diagnosis of perihilar cholangiocarcinoma (PHCC) and GBC (n = 38; 79.2%), whereas patients with intrahepatic cholangiocarcinoma (ICC) were more likely to harbor IDH1-2/BAP1/PBRM1 mutations (n = 14; 60.9%)." (PMID 33297469, 2020). "For instance, mutations in the IDH1 and IDH2 genes, as well as alterations in the FGFR2 gene, are more commonly associated with intrahepatic cholangiocarcinoma." (PMID 40075667, 2025). "A recent study demonstrated that in intrahepatic cholangiocarcinoma, the overexpression of PFKP and the activation of AMPK resulted in IDH1 mutation in normal biliary cells." (PMID 40821334, 2025). "Ivosidenib (AG120), a small molecule and selective inhibitor, has been developed targeting the IDH1 mutation and has recently been approved by the FDA for use in advanced-stage and metastatic intrahepatic cholangiocarcinoma (iCCA)." (PMID 39156971, 2024). "Mutations in FGFR1, FGFR2, IDH1, IDH2, BAP1, and ARID1A are more commonly found in intrahepatic cholangiocarcinoma, while SMAD4 mutations are more commonly seen in extrahepatic cholangiocarcinomas." (PMID 35267556, 2022).
intrahepatic cholangiocarcinoma (continued). "In BTCs, especially intrahepatic cholangiocarcinoma, comprehensive molecular profiling has expanded precision oncology through actionable alterations such as FGFR2 rearrangements, IDH1 mutations, HER2 amplification/overexpression, BRAF V600E, NTRK fusions, and MSI-high/dMMR status." (PMID 42196390, 2026). "In gliomas, IDH1 mutation explains the adverse prognostic effect of older age18,19, while in intrahepatic cholangiocarcinoma patients with mutant IDH, there was no direct association with clinical outcome." (PMID 37741882, 2023). "A 39-year-old MS woman together with intrahepatic cholangiocarcinoma (IHCC) showed IDH1 R132C mutation in the tumor tissue but not in the normal liver tissue and peripheral blood." (PMID 35765075, 2022). "This therapy is the treatment approach commonly seen in the management of intrahepatic cholangiocarcinoma, which is associated with a high incidence of fibroblast growth factor receptor (FGFR) fusion mutations and dehydrogenase isocitrate (IDH)-1 and 2 mutations." (PMID 35911272, 2022). "In intrahepatic cholangiocarcinoma, a mutation in IDH1 (R132C) suggested that the downregulation of P2RX7 was associated with the release of sEVs, further supports that mutations in IDH1 promote the release of sEVs." (PMID 36710884, 2022). "Moreover, another study revealed that mutant IDH1 and 2, the most common genetic alterations found in intrahepatic cholangiocarcinoma, inhibit HNF4A expression, block hepatocyte differentiation and induce biliary cancer formation." (PMID 29899848, 2018). "IDH1 and IDH2 isoforms are frequently mutated in various cancers, including glioma, acute myeloid leukemia, thyroid carcinomas, cartilaginous tumors, and intrahepatic cholangiocarcinoma (ICC)." (PMID 40567251, 2025). "Despite representing some of the most common and investigated molecular changes in intrahepatic cholangiocarcinoma (iCCA), the prognostic role of FGFR and IDH1/2 alterations still remains an open question." (PMID 37168376, 2023). "Isocitrate dehydrogenase 1/2 (IDH1/2), BAP1, ARID1A and PBRM1 have been reported as the most frequent mutant genes in intrahepatic cholangiocarcinoma (ICC), and their relationships with clinicopathological features and prognosis were researched in this study." (PMID 32293336, 2020).
malignant glioma (55 papers, 2012 to 2025). A grade III or grade IV glioma arising from the central nervous system. "Approximately 12% of malignant gliomas express the IDH1 gene, and the R132H mutation accounts for 92.7% of IDH1 gene mutations." (PMID 40371327, 2025). "IDH1 mutations effectively enhanced accumulation of radiation-induced γH2AX foci in these malignant glioma cells." (PMID 37952042, 2023). "The NLR value below 4 was reported to predict better outcomes but only in GBM expressing the wild-type gene IDH1, one of the genes that is most frequently mutated in malignant gliomas." (PMID 38003396, 2023). "The FAT1-ROS-HIF-1 signaling pathway is activated by the IDH1 mutation, which suppresses malignant glioma." (PMID 35609054, 2022). "IDH1 mutations were associated with a better response to cytotoxic therapy and longer survival in malignant glioma patients." (PMID 34070746, 2021). "Recurrent mutations in the active site of IDH1, occurring in 12% of malignant gliomas, were first reported in 2008." (PMID 34638714, 2021). "A recent study reported that the IDH1-R132H mutation causes both a less aggressive phenotype and radiosensitization of human malignant glioma cells." (PMID 34070746, 2021). "Our previous study has also shown decreased NADPH production (and increased consumption) in IDH1-mutated malignant gliomas and its implications in 5-ALA fluorescence enhancement." (PMID 28939850, 2017). "For this purpose, re-setting target metabolomes based on new molecular classification of malignant gliomas (i.e., production of 2-hydroxyglutarate from IDH1 mutation), and subsequent prospective CSF profiling study is necessary." (PMID 29254157, 2017). "It was demonstrated that in malignant gliomas of WHO grades III/IV with the IDH1 mutation, MGMT promoter methylation was associated with prolonged Progression-free survival (PFS) with chemotherapy ± radiation therapy (RT) or RT-only groups." (PMID 27834917, 2016). "We evaluated the significance of these markers, that is, 1p/19q co-deletion, MGMT promoter methylation, and IDH1 mutations, in malignant glioma." (PMID 24160898, 2013). "In this study, we focused on 1p/19 co-deletion, MGMT promoter methylation status, and IDH1 mutations in patients with malignant glioma." (PMID 24160898, 2013). "The presence of mutations in IDH1 and IDH2 early in disease pathogenesis in malignant gliomas, myeloid malignancies, and cartilaginous tumors underscores the magnitude of the role of IDH1 and IDH2 mutations in tumorigenesis." (PMID 22885298, 2012). "IDH1 mutations are especially prevalent in malignant gliomas." (PMID 39534557, 2024). "IDH1 mutations were first reported in 2008 and occur in 12% of malignant gliomas." (PMID 36136867, 2022). "Yet, it still remains to be seen whether both mutational spectrums of IDH1/2 predict response of malignant gliomas to chemotherapy." (PMID 33552543, 2020). "Notably, pseudohypoxia through HIFα stabilization in malignant glioma is a known consequence of IDH1 R132H mutation status." (PMID 26934654, 2016). "Classification based on IDH1/2 mutation status and Ki-67 expression level could be more convenient for clinical application and guide personalized treatment in malignant gliomas." (PMID 26338964, 2015). "In conclusion, enhanced 5-ALA fluorescence is associated with IDH1 mutations in malignant gliomas." (PMID 26008980, 2015). "The results of this study suggest that IDH1 mutation may be associated with polySia expression pathways in malignant gliomas." (PMID 25164322, 2014). "Despite its obvious association with tumorigenesis, the relationship between IDH1 mutation and good prognosis for malignant glioma is yet unknown." (PMID 24160898, 2013). "Due to the fact that almost all patients with a malignant glioma receive a single treatment or a combined therapy it is difficult to specify whether IDH1 mutation is associated with a less aggressive phenotype or directly linked to increased sensitivity to therapy." (PMID 31242696, 2019).
malignant glioma (continued). "Up to this point, attempts to correlate survival in malignant gliomas with genetic and biomolecular aspects of the tumor have only made very limited advances, with the exception of IDH-1." (PMID 38791312, 2024). "The high AUC values (0.719 for TBF and 0.729 for nTBF) suggest ASL perfusion efficiency in the differential diagnosis of malignant gliomas with different IDH1 statuses, which is of fundamental prognostic value in this group of patients." (PMID 35741254, 2022). "In an examination of PE in malignant gliomas using multiple regression analysis, IDH1-R132H status emerged as the only significant independent factor with a relationship with PE." (PMID 36514578, 2022). "The ROC-analysis revealed sufficient specificity and sensitivity for the differential diagnosis of malignant gliomas with different IDH1 statuses." (PMID 35741254, 2022). "In malignant gliomas, the combination of IDH1 mutations and MGMT methylation status is more predictive of survival than either IDH1 or MGMT alone." (PMID 34638714, 2021). "IDH1 mutation is observed in more than 80% of WHO II and WHO III grade malignant gliomas and secondary GBM, while they are very rare in primary GBM, ependymomas and hepatocellular astrocytoma." (PMID 32886667, 2020). "In a previous study, the effect of IDH1 mutant protein on radiobiological behavior was carried out with U-251MG, U-343MG, and LN-229 malignant glioma cell lines." (PMID 31242696, 2019). "Of note, we opted for YFP* as a more appropriate control because the upregulation of wild-type IDH1 promotes aggressive growth of malignant glioma." (PMID 30416682, 2018). "Using genetically engineered malignant glioma cells harboring wild type (U87MG-IDH1WT) or mutant (U87MG-IDH1R132H) IDH1, we demonstrated a lag in 5-ALA metabolism and accumulation of protoporphyrin IX (PpIX) in U87MG-IDH1R132H cells." (PMID 26008980, 2015). "This study reports the experience of treating 10 patients with recurrent malignant gliomas located in deep areas or functionally relevant structures of the brain using sPDT; here, patients without the IDH1/2 gene mutation predominated (7 out of 9 examined)." (PMID 39539750, 2024). "Additionally, we examined the influence of molecular markers for prognostic significance in malignant glioma, including MGMT promotor methylation status, IDH-1/2 mutation and loss of ATRX on overall survival." (PMID 35183162, 2022). "As expected, none of the patients over 12 years old showed any IDH1/2 gene point mutations apart from a biomolecular resemblance to malignant gliomas arising in > 14-year olds and adults." (PMID 33128602, 2021). "Our study also showed significantly greater MGMT methylation in malignant glioma patients with IDH1 mutations than in those without (P < 0.0001)." (PMID 24160898, 2013). "Another study on 119 patients found that IDH1-wild type show reduced neurocognitive functions compared with those with IDH1-mut malignant gliomas, and that lesion volume is inversely associated with neurocognitive functions for patients with IDH1-wild type, but not IDH1-mut tumors." (PMID 39722690, 2024). "Furthermore, we found no somatic mutation in Idh1, Idh2, or H3f3a (mutated in pediatric GBMs) in malignant gliomas and GBMs from all three models, which were more similar to the human IDH-WT GBMs without exhibiting G-CIMP 22,24." (PMID 32699356, 2020). "Thus, in addition to the conventional pathological diagnosis, classification of patients on the basis of the presence or absence of IDH1 mutations should be considered for patients with malignant glioma (GBM and AA)." (PMID 24160898, 2013). "Mutations in NADP(+)-dependent isocitrate dehydrogenases coded by the IDH1 and IDH2 are seen in the majority of malignant gliomas." (PMID 38686271, 2024).